TGM2 (transglutaminase 2)
Diseases named in the same sentence as TGM2 in open-access papers (continued):
Sharing a sentence is not in itself a finding about the gene and the disease.
tumor (continued). "More recently, we constructed a miRNA expression signature of RCC clinical specimens and successfully identified tumor suppressive miR-1285 targeting transglutaminase 2 (TGM2)." (PMID 22766839, 2012). "BNIP3 and TGM2 expression was scored as high or low, based on the number of tumor cells stained and the staining intensity." (PMID 22458929, 2012). "Collectively, our results establish TGM2-mediated GPX4 serotonylation as a key mechanism driving GC progression through ferroptosis resistance, highlighting its potential as both a diagnostic biomarker and a therapeutic target within the neural-tumor axis." (PMID 42049702, 2026). "As with normal brain vasculature, endothelial cells of the tumour vasculature also express TGM2." (PMID 40610434, 2025). "Similarly, the TGM2 inhibitor simultaneously reduced H3Q5ser and H3cit in neutrophils from the livers of tumor-bearing mice in vivo." (PMID 40231471, 2025). "High TGM2 expression in LUSC is associated with poorer prognosis, and high TGM2 expression is strongly associated with pro-tumor inflammation and may increase susceptibility to immunotherapy." (PMID 39910672, 2025). "It phenocopied the parent tumor by having elevated TGM2 expression." (PMID 41142754, 2025). "Upregulation of Tgm2 and Rab7b promotes tumor cell autophagy." (PMID 39796281, 2025). "TGM2-deficient mice exhibit impaired T cell activation and a reduced the proportion of MDSC/tumor-associated macrophage (TAM) cells, significantly enhancing anti-tumor immunity within the TME." (PMID 41050683, 2025). "High TGM2 mRNA was also present in tumour endothelial cells." (PMID 40610434, 2025). "Furthermore, Gem-R tumor cells exhibited increased secretion of ATP, NH4+, and TGM2 compared to adjacent non-tumor tissues." (PMID 41469519, 2025). "Consistently, tumor tissues from Gem-R PDAC patients demonstrated elevated TGM2 expression." (PMID 41469519, 2025). "Prior studies indicate transglutaminase 2 (TGM2) regulates the tumor microenvironment, but its mechanisms in driving LUSC progression and immune evasion remain unclear." (PMID 41050683, 2025). "Increased frequency of T cells and NK cells in the orthotopic tumor in the Tgm2 knockout mice supported an increase in immune activation, especially with an increase in both the frequency of CD4+ T cells and their elevated expression of the exhaustion markers PD-1 and LAG3." (PMID 40777010, 2025). "We compared TGM2 mRNA expression levels in both tumor and normal tissues." (PMID 38474044, 2024). "In orthotopic xenograft mouse models of gastric and pancreatic cancer, platelet-derived serotonin upregulated the PD-L1 expression in tumor cells via histone serotonylation mediated by transglutaminase 2, impaired the function of intra-tumoral CD8+ T cells, and accelerated tumor growth." (PMID 38334648, 2024). "To further investigate the molecular signaling pathways of MMP inhibition by cysteamine treatment, we conducted western blots for transglutaminase 2 (TGM2) and extracellular matrix proteins such as N-cadherin (an invasion promoter) and E-cadherin (a tumor suppressor)." (PMID 38893149, 2024). "In addition to participating in the regulation of ECM adhesion, TGM2 is involved in tumor formation." (PMID 37115802, 2023). "TGM2 expression was upregulated in matched tumor samples in comparison to normal tissue." (PMID 37443286, 2023).
tumor (continued). "We determined the intensity of TGM2 protein expression in epithelial cells of the tumor." (PMID 37443286, 2023). "Moreover, the prognosis of advanced-stage CRC with strong TGM2 expression was significantly worse when patients were uniformly treated with oncologic tumor resection and adjuvant chemotherapy." (PMID 37443286, 2023). "Treatment of mice with TGM2 inhibitors exhibited a significant deceleration of tumor progression." (PMID 37443286, 2023). "Additionally, interference of circ_0081001 declined the expression of circ_0081001 and TGM2 while promoted the expression of miR-494-3p in resected tumor tissues." (PMID 33435987, 2021). "In vivo, based on orthotopic xenograft mouse models, downregulating the expression of TGM2 by siRNA or shRNA could restrain the tumor growth and improve the treatment effect of Gemcitabine in PDAC." (PMID 33637086, 2021). "It remains uncertain, whether TGM2 has a pro- or antitumorigenic role, if it promotes tumor cell survival or apoptosis, and whether epithelial–mesenchymal transition and invasion are supported by TGM2." (PMID 34103685, 2021). "Likewise, a downregulation of TGM2 was found in aggressive tumors and metastasis, while overexpression of TGM2 led to reduction in tumor incidence and progression." (PMID 34206882, 2021). "Therefore, it is likely, that different cell types respond differentially to alterations in distinct TGM2 functions, which are also influenced by the individual tumor microenvironment." (PMID 34103685, 2021). "Knowing that serotonylation modifies protein activity and recycling in the cell, TGM2 decrease in HB could have some implications in the regulation of the tumor cell metabolism." (PMID 34943977, 2021). "TGM2 in the tumor stroma can inhibit tumor growth and metastasis." (PMID 32923383, 2020). "Recent studies have revealed that elevated TGM2 expression is a factor in tumor survival." (PMID 29785022, 2018). "Additionally, inflammatory signals have been shown to upregulate TGM2 expression via NF-κB activation in tumour cells." (PMID 30393774, 2018). "These authors described tumor cell migration/invasion in response to siRNA silencing of TGM2." (PMID 30108682, 2018). "In addition, inhibition of the GTPase activity of TGM2 prevents autophagic protein degradation as well as colony formation, supporting the conclusion that TGM2 contributes to tumor suppression, at least in part, by promoting autophagy." (PMID 26956429, 2016). "The predominant activity of TGM2 in specific contexts may determine whether it functions as a tumor-promoting or -suppressive protein." (PMID 26956429, 2016). "Importantly, the combination of rapamycin and a TGM2 blockade promoted tumor regression in an MCF-7-xenograft tumor model." (PMID 26872016, 2016). "TGM2-mediated chemoresistance was shown to regulate ECM proteins for tumor cell survival." (PMID 26872016, 2016). "We have demonstrated a promising strategy of targeting both mTORC1 and TGM2 in vitro and in a xenograft tumor model, and we observed that this combined approach may have resulted in tumor regression." (PMID 26872016, 2016). "TGM2 suppressed colony formation in soft agar and tumor formation in a xenograft mouse model." (PMID 26956429, 2016).
tumor (continued). "Our data indicated that upregulation of oncogenic TGM2 may be due to downregulation of tumor suppressive miR-1285 in human RCC progression." (PMID 22294552, 2012). "Downregulation of tumor suppressive miR-1285, which targets oncogenic genes including TGM2, might contribute to RCC development." (PMID 22294552, 2012). "It was reported that IL1B increased the expression level of TGM2, which might be involved in establishing a barrier to tumor spreading." (PMID 20142997, 2010). "Moreover, a strong TGM2 expression was more frequent in patients with advanced tumor stages." (PMID 37443286, 2023). "Whether TGM2 was expressed in tumor epithelium or in the tumor microenvironment remained unclear." (PMID 37443286, 2023). "High expression of TGM2 might be a target for tumor inhibition." (PMID 37993945, 2023). "Therefore, we investigated whether TGM2 expression correlates with the absence or presence of tumor metastasis, age, sex, and body mass index (BMI) in patients affected by this pathology using the UALCAN database." (PMID 35725560, 2022). "In addition to cytoplasmic TGM2 staining, we observed nuclear localization of TGM2 in tumor cells." (PMID 34103685, 2021). "In addition, inhibition of TGM2 may alleviate stroma fibrosis to facilitate the infiltration of immune effector cells and the entrance of drugs, can also restrain the tumor growth as previous studies reported." (PMID 33637086, 2021). "Moreover, CLIC3 was detected in the tumour stroma that also stained positively for αSMA and TGM2." (PMID 28198360, 2017). "Interestingly, the GTP binding site mutant (R580A) completely ablated the tumor suppressive effect of TGM2 in colony formation, whereas the transamidation site mutant (C277S) displayed only a slightly reduced tumor suppressive effect compared to wild-type TGM2." (PMID 26956429, 2016). "Although our HMEC transformation model suggests that TGM2-mediated autophagy suppresses early events during tumor initiation, the autophagic function of TGM2 may promote tumor progression by facilitating the survival of established tumors under nutrient stress." (PMID 26956429, 2016). "The sample size was quite limiting, but we still could confirm a protective role for the tumor cell-associated TGM2 (albeit for the protein and not the gene) similar to the one reported in infiltrating tumors." (PMID 27600076, 2016). "Analysis using the GEPIA database revealed a significant positive correlation between TGM2 and NR3C1 expression in both normal and tumor tissues (R = 0.53, P = 7.6×10−60)." (PMID 41050683, 2025). "Genes such as HLA-B, TGM2 and GBP1 tend to exhibit high connectivity degrees across most tumor and normal regions." (PMID 39954675, 2025). "High TGM2 expression correlates with reduced OS and DFS, promoting tumor proliferation, migration, invasion, and resistance to apoptosis." (PMID 41050683, 2025). "Upon reaching GBM cells, the enzyme transglutaminase 2 (TG2) triggers Pep-TPE aggregation, generating fluorescence for high-resolution tumor imaging with an enhanced signal-to-noise ratio." (PMID 40806198, 2025). "Through analysis of the HPA database, we recognized remarkably higher expression levels of specific proteins, including AQP1, ITGA5, MAP3K8, PIK3R3, STC1, and TGM2, in HNSCC tumor tissues." (PMID 38688945, 2024). "To further explore the mechanism through which TGM2 regulates MDCK tumor-forming cells, we used real-time PCR to evaluate the expression of common downstream genes for the tumor-forming response signaling pathway." (PMID 37115802, 2023). "There is a fine regulation of GBM cell proliferation, since we see, that the upregulation of the BDKRB2 and TGM2 mRNAs leads to stimulation of the EMT, which is necessary for tumor progression migration and metastasis." (PMID 36354672, 2022).
tumor (continued). "Interestingly, high TGM2 expression appears significantly associated with an increase in terms of survival rate (Log-rank p = 0.014), but it was also found to be significantly and positively associated with the SKCM tumor stages (F-value = 7.75; Pr(>F) = 4.99e-06)." (PMID 35725560, 2022). "The interest in TGM2 transcription is supported by the evidence that isoforms are distinctly involved in EMT, tumor invasion and metastasis 6,15,16." (PMID 34975314, 2022). "miR-19a was reported to have a role in invasion and metastasis in vitro by inhibiting Transglutaminase-2 (TG2), a critical cross-linking enzyme in the extracellular matrix (ECM) and tumor microenvironment." (PMID 33669508, 2021). "In this study, we used an siRNA-based approach to investigate the contribution of the protein cross-linking enzyme transglutaminase-2 (TG2) to matrix remodelling and biomechanical properties of the tumour microenvironment." (PMID 31117256, 2019). "Indeed, non-immune stromal cells in the VPr tumor expressed significantly more Tgfb1 and Tgm2 (encoding a collagen crosslinking enzyme), and scored high for a fibroblast transforming growth factor-β response signature (PMID: 29443960), which included genes related to myofibroblast function." (PMID 30824837, 2019). "Herein, we have shown that TGM2 upregulation promotes EMT in HCC cells, and that TGM2 knockdown inhibits the promotion of EMT by activated hepatic stellate cells in HCC cells, confirming the importance of TGM2 in tumour progression." (PMID 30393774, 2018). "Some of these genes, including GDF15, TGM2, VEGFA and ZNF385A were also up-regulated in primary tumor cells from patient 32 after co-culture with N-MSCs." (PMID 29503225, 2018). "Inhibition of TGM2 upregulation thus promises a unique paradigm in HCC treatment, aimed at suppressing tumour progression by a remodelling of tumour milieu." (PMID 30393774, 2018). "To reconcile the efficacy of combining mTORC1 and TGM2 inhibition in tumor cells with mTORC1-hyperactive cells in vivo, we developed an MCF-7-luciferase-tagged xenograft tumor model." (PMID 26872016, 2016). "The connection including TGM2, IL1B, and PLAU and the connection including RAB25, SNAI1, and CDH1 were suggested to be related to tumor invasion by IPA." (PMID 20142997, 2010). "Specifically, we found that GPX4 is serotonylated by TGM2 at residues Gln55 and Gln77, which increases GPX4 protein stability by attenuating its ubiquitin-mediated degradation, thereby conferring resistance to ferroptosis and facilitating tumor growth." (PMID 42049702, 2026). "In HCC, elevated TGM2 expression correlates with poor differentiation, high levels of the HCC marker alpha-fetoprotein (AFP), and advanced tumor stage, with pharmacological inhibition of serotonylation suppressing tumor growth." (PMID 41424854, 2026). "TGM2_v2 was several folds higher both in low-grade (Grade 1–2) and Grade 3 differentiated tumours compared with that in CIP, suggesting that TG2 may be a marker of malignancy." (PMID 37160910, 2023). "For instance, the TGM2 promoter region contains various responsive elements able to induce or inhibit TG2 expression during inflammation and hypoxia, two key oncogenic processes characterizing the tumour microenvironment (TME)." (PMID 37898636, 2023). "Additionally, trichostatin A, another HDAC inhibitor, restored the expression of the differentiation protein transglutaminase 2 (TG2), usually repressed by MYCN in NB cells, resulting in reduced tumor volume in the same mouse model." (PMID 38069407, 2023).
tumor (continued). "There were also genes that are of insignificant expression in tumor cells that increase in expression in KO cells, e.g. THBS3, IL2RG, SPRR3, TGM2, HMOX1 and TMEM62 or are lower in expression in tumor cells and significantly decreased in KO cells such as MAN1A1, CES1, STCBP6, SIVA1 and TMEM40." (PMID 31797958, 2019). "On the contrary, in our experimental set up WA decreased EMT-related components of the TGF-β signaling pathway (TGFA, TGFBR2, CDH11), as well as TGM2, HIF1A, several TNFSF family members and ANGPTL2, which stimulate tumor promoting pro-inflammatory responses and a hypoxic microenvironment." (PMID 24498382, 2014). "In an independent dataset of oral samples (set 6), TGM2 expression was higher in lymph node metastases than in the corresponding primary tumours and in a separate set of non-metastatic oral SCCs." (PMID 23765377, 2013). "TGM2 was strongly expressed in tumor lesions A (T1N0M0), B (T2N0M0) and C (T3N0M0), whereas no expression was observed in normal tissue (D)." (PMID 22294552, 2012). "In addition, further work on the methylation status of the TGM-2, MMP-2 and CD24 genes in other multi-factorial human non-neoplastic diseases such as diseases involving scarring or aberrant wound healing are warranted." (PMID 21359202, 2011). "The identified genes are involved in drug transport and detoxification (ABCB1, DNAJC15, GSTP1, RAB6C), DNA damage repair (BRCA1) as well as tumor cell proliferation/invasion (APC, CDH1, ESR1, HIC, PLAU, RASSF1, SULF2, TGM2)." (PMID 20544021, 2010). "The third connection including TGM2, IL1B, and PLAU was suggested to be tumor invasion." (PMID 20142997, 2010). "Transglutaminase 2 (TG2) is a ubiquitously distributed enzyme that catalyzes the transamidation of proteins in a calcium-dependent manner and regulates various biological processes, such as ECM accumulation, tumor progression, cell differentiation, and cell death." (PMID 35740367, 2022). "As for the HNSCC cell lines UM-SCC19 and UM-SCC47, they showed the opposite effect by downregulating the expression of CLEC3B and CCRL1 in the PFs (*** p < 0.001) after tumor cell-fibroblast co-culturing while not affecting the RF marker expression of TGM2 and MGP in the RFs." (PMID 36232952, 2022). "Therefore, MT-MMPs, TGM2 and E2F1 might be conjoined by pathological processes in the liver to trigger inappropriate cell proliferation and tumour development." (PMID 33541355, 2021). "However, the roles of TGM2 in the regulation of the tumor microenvironment of GC have not been elucidated." (PMID 32467608, 2020).
tumor (continued). "Moreover, the finding of detergent-resistant retention of DAB4-targeted radioactivity in EL4 tumors only when 90Y-DOTA-DAB4 was given after chemotherapy rather than by itself suggests that tumor accretion of DAB4-targeted radioactivity resulted from increased transglutaminase 2 activity." (PMID 19247485, 2009). "The mRNA levels of TGM2, USP18, DDX58, PARP9, STAT1 and STAT2 were not significantly different between ER--tumor tissues and their corresponding tumor-adjacent tissues." (PMID 29416786, 2018).